LHX2 (LIM homeobox 2)
Diseases named in the same sentence as LHX2 in open-access papers (continued):
Sharing a sentence is not in itself a finding about the gene and the disease.
retinal disease (3 papers, 2019 to 2023). "As a result, Lhx2 loss-of-function affects genes involved in the cell cycle checkpoints, DNA replication, retinal disease phenotypes and the Notch signaling pathway, consistent with previous findings." (PMID 31044167, 2019). "We show that in the RPE, the primary tissue affected in AMD, LHX2 is required for OTX2 expression and both co-bind multiple cis-regulatory regions controlling the transcriptional program that defines RPE identity, including genes involved in monogenic and complex retinal diseases." (PMID 36649236, 2023).
schizophrenia (3 papers, 2016 to 2023). A major psychotic disorder characterized by abnormalities in the perception or expression of reality. "LHX2 is down-regulated in the hippocampus of schizophrenia patients, while our data suggest that it is upregulated in the same region during gestation, a discrepancy that is likely explained by the developmental time point at which the gene was measured." (PMID 32497066, 2020).
autism spectrum disorder (2 papers, 2023 to 2025). A spectrum of developmental disorders that includes autism, and Asperger syndrome. "Additionally, we observed ectodermal EtOH-induced alterations in several genes, such as LHX2, SHANK2, TRIO, ZMYND8, ARX, NRXN3 and SEMA5A, that have also been associated with autism spectrum disorder (ASD) (SFARI Gene Database, 2024; accessed: 1, August, 2024)." (PMID 40401629, 2025).
holoprosencephaly (2 papers, 2015 to 2025). Holoprosencephaly (HPE) is a complex brain malformation resulting from incomplete cleavage of the prosencephalon, occurring between the 18th and 28th day of gestation, and affecting both the forebrain and face, which results in neurological manifestations and facial anomalies of variable severity. "Many of the altered genes, including BMP4, FGF8, SIX3 and LHX2, have previously been associated with PAE and phenotypes of FASD, like defects in heart and corpus callosum development as well as holoprosencephaly." (PMID 40401629, 2025).
microcephaly (2 papers, 2023 to 2025). A congenital or acquired developmental disorder in which the circumference of the head is smaller than normal for the person's age and sex. "Furthermore, dorsal forebrain conditional Lhx2 mutant mice have dramatically smaller cerebral cortices when compared to controls, again resembling with human microcephaly phenotype observed in patients with LHX2 variants." (PMID 38094004, 2023). "In this study, I focus on several homeobox genes (ARX, LHX2, MEIS2, NKX2-1, OTX1, OTX2, and PAX6) implicated in the pathogenesis of microcephaly." (PMID 38094004, 2023).
pancreatic cancer (2 papers, 2015 to 2016). "Less miR-124 expression results in higher expression of its target LIM homeobox-2 (Lhx2), leading to pancreatic cancer cell stemness." (PMID 27240340, 2016). "Although high levels of LHX-2 expression were found in chronic myelogenous leukaemia (CML) and a variety of human solid tumors, including gastrointestinal cancer, pancreatic cancer and kidney cancer, the expression and regulation of LHX2 in NSCLC carcinogenesis has not yet been defined." (PMID 26189214, 2015).
schizencephaly (2 papers, 2010 to 2021). "We hypothesized that mutations in LHX2 might give rise to schizencephaly given the important role of LHX2 in cortical patterning." (PMID 20949537, 2010). "LHX2, another gene expressed in the developing forebrain, specifies cortical fate in the hippocampus and neocortex [Hebert and Fishell, 2008] and has been hypothesized as a potential candidate gene for schizencephaly." (PMID 20949537, 2010). "Analysis of sequencing of the LHX2, HESX1, and SOX2 exons and exon–intron junctions in 97 cases of schizencephaly did not reveal mutations that were likely to be pathogenic." (PMID 20949537, 2010).
acute leukemia (1 paper, 2022). A clonal (malignant) hematopoietic disorder with an acute onset, affecting the bone marrow and the peripheral blood. "Constitutive expression of Lhx2 in natural hematopoietic progenitor/stem cells in vivo led to a myeloproliferative disorder and caused acute leukemia, which implies that the iHPCs generated in our study are different from these cells, as our iHPCs did not cause myeloid proliferation." (PMID 34893754, 2022).
Alzheimer disease (1 paper, 2025). A progressive, neurodegenerative disease characterized by loss of function and death of nerve cells in several areas of the brain leading to loss of cognitive function such as memory and language. "In Alzheimer’s disease, plasma cf-DNA contains neuronal tissue-specific methylated genes such as LHX2 at CpG sites 1 and 5, suggesting potential as a peripheral neurodegeneration marker." (PMID 41041342, 2025).
breast tumor (1 paper, 2023). "In addition, several papers have reported aberrant gene body methylation, including introns in cancer, e.g., hypermethylation of EGFR, LHX2, SOX9, and RFX1 introns in breast tumor tissue compared to paired adjacent tissue." (PMID 37296582, 2023).
congenital nystagmus (1 paper, 2009). Nystagmus present at birth or caused by lesions sustained in utero or at the time of birth. "Alternatively, looping could be a result of the lhx2-mutation-related ipsilateral projection of the optic nerves, which has been shown to cause two specific oculomotor instabilities: reversed optokinetic response (OKR) and congenital nystagmus (CN)." (PMID 19672291, 2009).
corneal dystrophies (1 paper, 2023). "Likewise, for COL8A1, an ECM component linked to AMD and to corneal dystrophies, 4 sites were bound by both OTX2 and LHX2 and 3 only by OTX2." (PMID 36649236, 2023).
esophageal squamous cell carcinoma (1 paper, 2022). Esophageal squamous cell carcinoma (ESCC) is a type of esophageal carcinoma (EC) that can affect any part of the esophagus, but is usually located in the upper or middle third. "LHX2 dysregulations have been found to present in cancers, but the function of LHX2 in esophageal squamous cell carcinoma (ESCC) remains unknown." (PMID 36011368, 2022).
hepatoblastoma (1 paper, 2023). Hepatoblastoma (HB) is a malignant hepatic tumor and is the most common pediatric liver cancer. "However, the downregulation of LHX2 correlated with intermediate, high-risk tumors and low patient survival in hepatoblastoma, which indicated that LHX2 plays complex roles in human cancers." (PMID 37345110, 2023).
leukemia (1 paper, 2024). A malignant (clonal) hematologic disorder, involving hematopoietic stem cells and characterized by the presence of primitive or atypical myeloid or lymphoid cells in the bone marrow and the blood. "To obtain clues about the inhibitory effect of Lhx2 in human cells, we used human leukemia cell lines, since we previously found that Lhx2 inhibits the proliferation of human T-cell leukemia cell lines, Jurkat and CCRF-CEM." (PMID 39474350, 2024).
liver cancer (1 paper, 2022). An epithelial or non-epithelial malignant neoplasm that arises from the liver. "Inversely, as a tumor suppressor, LHX2 inhibits tumor development by blocking the MAPK/ERK and Wnt/beta-catenin signaling in adult and pediatric liver cancers." (PMID 36011368, 2022).
lung carcinoids (1 paper, 2022). "Additionally, LHX2 has also been recognized as a novel potential biomarker of lung carcinoids with invasive characteristics." (PMID 36011368, 2022).
lung carcinoma (1 paper, 2019). "It has been recently found that miR-124 can inhibit the migration and invasiveness of lung cancer cells by inhibiting LHX2 expression." (PMID 31632439, 2019).
medulloblastoma (1 paper, 2025). A malignant, invasive embryonal neoplasm arising from the cerebellum. "BMP signaling and LHX2 gain-of-function expression led to enriched stemness and associated chemoresistance in medulloblastoma cultures." (PMID 40148468, 2025). "The molecular pathway that couples LHX2 function to BMP signaling in medulloblastoma deepens our understanding this malignancy." (PMID 40148468, 2025). "In-mouse orthotopic transplantation of paired primary/recurrent Group 4 medulloblastoma cell populations, correspondingly expressing LHX2-low/BMP-low signaling and LHX2-high/BMP-high signaling, ascribed to the latter (high) group more efficient tumor propagation and spinal cord metastatic potential." (PMID 40148468, 2025).
Obesity (1 paper, 2021). Accumulation of substantial excess body fat. "For example, the molecular functional mechanisms of CEP120, TSC22D2, Al090771.1 and LHX2 have not been yet linked to obesity, fat distribution and obesity comorbidities." (PMID 34072523, 2021).
pituitary deficiency (1 paper, 2022). "LHX2 mutations can result in pituitary hormone deficiency, although it is uncommon that a mutation in LHX2 alone can cause pituitary deficiency and developmental ocular abnormalities." (PMID 35546872, 2022).
RASopathy (1 paper, 2025). Developmental syndromes caused by germline mutations (or in rare cases by somatic mosaicism) in genes that alter the Ras subfamily and mitogen-activated protein kinases that control signal transduction. "One of these is LZTR1, a known RASopathy gene that targets proteins in the RAS pathway for degradation, Similarly, LHX2 (pLI = 0.99), encodes a transcriptional activator; mouse knockouts produce CHD." (PMID 40127276, 2025).
small cell lung carcinoma (1 paper, 2022). Small cell lung cancer (SCLC) is a highly aggressive malignant neoplasm, accounting for 10-15% of lung cancer cases, characterized byrapid growth, and early metastasis. "LHX2 regulating progenitor differentiation and proliferation was also found to be overexpressed in small-cell lung cancer and prostate cancer." (PMID 36159187, 2022).
tumor (27 papers, 2013 to 2025). "Besides the critical physiologic role in embryonic development, the aberrant expression of LHX2 is associated with primary tumor growth and metastasis." (PMID 37345110, 2023). "Depletion of LHX2 in these recurrent tumor cells suppressed both BMP signaling and tumor propagation in vivo." (PMID 40148468, 2025). "HOXA5, WT1, and LHX2 are fibroblast specific motifs that are drivers of tumor microenvironment remodeling, and their potential targets were highly correlated with collagen - containing extracellular matrix in KEGG analysis." (PMID 38702814, 2024). "We found that the CD3 level in the si-LHX2 group was significantly lower than that in the NC group, which indicates that the expression of tumor-infiltrating T cells was positively correlated with the expression level of LHX2." (PMID 37345110, 2023). "In vitro and in vivo functional experiments demonstrated that the knockdown of LHX2 significantly inhibited ESCC cells’ proliferation, tumor growth, migration, invasion, and metastasis, while the overexpression of LHX2 exerted the opposite effects." (PMID 36011368, 2022). "In parallel, the average weight of tumours was significantly higher in LHX2-overexpressed tumours than in control tumours." (PMID 35864158, 2022). "Consistent with function of LHX2 in cancers in the previous studies, we consider that LHX2 mainly performs a tumor-promoting function in cancers." (PMID 36011368, 2022). "Loss- and gain-of-function experiments demonstrated that the knockdown of LHX2 markedly inhibited ESCC cells’ proliferation, migration, invasion, tumor growth and metastasis, whereas the overexpression of LHX2 had the opposite effects." (PMID 36011368, 2022). "Recent studies revealed LHX2 promotes tumour development and is highly expressed in a variety of human cancer types, including pilocytic astrocytoma, chronic myelogenous, leukaemia and pancreatic cancer." (PMID 35864158, 2022). "KRT15 marked a subset of KRT14high tumor nests, LHX2 marked the nucleus of cells along the outer periphery of KRT14high tumor nests, and ACTA2 marked the outer periphery of KRT14low tumor nests." (PMID 35687691, 2022). "Our study demonstrates that LHX2 acts as a tumor-promoting role in ESCC progression and provides a new potential target against ESCC." (PMID 36011368, 2022). "Genomic expression profiling of the TCGA database reveals LHX2 level is increased in many solid tumours, and higher expression of LHX2 predicted poor survival in several solid tumours, suggesting its potential oncogenic role in tumour development." (PMID 35864158, 2022). "At the cellular level, USP18, TLR7, IL21R, GCNT1 and CHST7 were expressed in various tumor cell lines, while the expression of LHX2, IL2RA and IL5RA was low in CCLE." (PMID 34001679, 2021). "To identify the phenotypes of LHX2 and miR-129-5p overexpression, we performed rescue experiments on tumor growth and metastasis in orthotopic xenograft models." (PMID 31724536, 2019). "To explore the molecular mechanisms of LHX2 during tumor progression, we assessed several critical regulators of the Akt/mTOR pathway." (PMID 31724536, 2019). "As expected, this is first evidence of identifying the cytostatic role of miR-1238 in NSCLC cells, further improving our understanding of the tumor-promoting function of LHX2." (PMID 26189214, 2015). "Analysis of bulk expression data from both tumor cohorts identified high variance in expression levels of several H3K27me3-associated genes in both PFAs and H3K27M DMGs with greatest variability in homeobox genes including HOXA2, HOXA4, and LHX2.." (PMID 36759899, 2023). "The results show that LHX2 mainly assisted immune-related pathways and tumor-related pathways." (PMID 37345110, 2023). "In addition, a decreased level of E-cadherin and an increased level of Vimentin were determined in LHX2-overexpressing tumours." (PMID 35864158, 2022).
tumor (continued). "Taken together, these findings suggest that LHX2 may enhance tumor growth and metastasis by transcriptionally upregulating the SERPINE2 expression in ESCC." (PMID 36011368, 2022). "Furthermore, AZD4547 treatment significantly revised the accelerated tumour growth and metastasis by LHX2 overexpression in vivo." (PMID 35864158, 2022). "In NSCLC, miR-1238 also suppressed tumor cells by targeting LHX2." (PMID 36098705, 2022). "Tumour growth promotion was observed in LHX2-overexpressing cells compared to control cells." (PMID 35864158, 2022). "Collectively, LHX2 facilitates ESCC tumor progression, and it could be a potential therapeutic target for ESCC." (PMID 36011368, 2022). "Furthermore, miR-144 overcomes resistance to cisplatin (CDDP) through targeting of LIM homeobox 2 (Lhx2), leading to apoptosis and inhibiting invasion in tumor cells." (PMID 32276343, 2020). "However, mice inoculated with miR-129-5p that overexpressed LHX2 showed increased tumor sizes and weights." (PMID 31724536, 2019). "The number of tumor foci in the lungs significantly decreased when LHX2 expression was silenced." (PMID 31724536, 2019). "Herein, we found that LHX2 negatively regulates autophagy, which may contribute to tumor progression." (PMID 31724536, 2019). "Previous studies have demonstrated that LHX2 functions as an oncogene during tumor development, but the expression and function of LHX2 in OS remain unknown." (PMID 31724536, 2019). "LHX2 is downregulated in infratentorial tumours as already reported." (PMID 23947815, 2013). "However, it is noteworthy that LHX2 was found to be downregulated in liver tumors, a phenomenon that may accelerate anti-tumor progression." (PMID 38702814, 2024). "Moreover, we explored the role of LHX2 in tumour metastasis in vivo via a lung metastasis model." (PMID 35864158, 2022). "Furthermore, FGF/FGFR trapping by AZD4547 could block the LHX2/FGF1-induced promotion of tumour growth and metastasis." (PMID 35864158, 2022). "However, how SERPINE2 mediates LHX2-promoting tumor growth and the metastasis of ESCC still remains unclear, and our study failed to clarify the clinical significance of LHX2 and SERPINE2 in ESCC." (PMID 36011368, 2022). "In addition, LHX2 is closely related to tumorigenesis and tumor progression." (PMID 36011368, 2022). "The results suggested that LHX2 may play a tumor-promoting role in NSCLC." (PMID 26189214, 2015). "As a protective factor, LHX2 induces the expression of inhibitors targeting WNT and MAPK/ERK signaling pathways to stop tumor progression." (PMID 38702814, 2024). "high PLP2+ Tumor EPCs score group highly expressed ATF6, ELF1, ERG and PLAGL1 genes, while low PLP2+ Tumor EPCs score group highly expressed ATF5, TBX21, SPIB, LHX2 and JUND genes." (PMID 38482016, 2024). "Overall, these data strongly suggest that LHX2 accelerates ESCC cell proliferation and tumor growth." (PMID 36011368, 2022). "As expected, LHX2 silencing dramatically suppressed the tumor growth of ESCC cells, and LHX2 overexpression facilitated tumors with greater volumes and heavier weights with a higher proliferation rate." (PMID 36011368, 2022). "In summary, LHX2 is significantly upregulated in ESCC tissues and promotes ESCC tumor growth and metastasis by augmenting the expression of SERPINE2." (PMID 36011368, 2022). "We found that LHX2, BMP-5 and GDF11 had complex interactions with other missing proteins and BMP-5 had both tumor suppressing and tumorigenic roles." (PMID 32050622, 2020). "Therefore, our findings demonstrated that LHX2 may play a tumor-promoting role in NSCLCs." (PMID 26189214, 2015). "During our analysis the most prominent differences connected with the location of the tumor were noted for the IRX2, PAX3, CXCL14, LHX2, SIX6, CNTN1 and SIX1 genes." (PMID 26497896, 2015). "A group of 4 genes (ARX, GPR17, LHX2 and CXCL14) well stratified LGGs between infratentorial and supratentorial tumours." (PMID 23947815, 2013).
tumor (continued). "Spatial transcriptomics in tumor areas, complemented by transcriptomic analysis of multiple cell models, identified BMP-dependent transcriptional induction of the LIM-homeobox gene 2 (LHX2)." (PMID 40148468, 2025). "In our study, we found that the level of LHX2 was increased considerably in ESCC tissues compared with adjacent normal tissues, and it was shown that LHX2 overexpression promoted tumor growth and metastasis, whereas LHX2 knockdown lessened the growth and metastasis of ESCC." (PMID 36011368, 2022). "The relationship between LHX2 and tumor development has not yet been identified." (PMID 31632439, 2019). "As a transcription factor, LHX2 may transcriptionally regulate the expression of a group of tumor-related genes, SERPINE2 did not completely rescue the phenotype induced by LHX2 knockdown in ESCC, we speculate that there may be other gene mediating the roles of LHX2 in the malignant phenotypes." (PMID 36011368, 2022).